IL6 (interleukin 6)
Diseases named in the same sentence as IL6 in open-access papers (continued):
Sharing a sentence is not in itself a finding about the gene and the disease.
malnutrition (continued). "Nevertheless, the significance of low serum albumin is multiple, including malnutrition but also chronic inflammation (IL6-dependent liver synthesis), as well as haemodilution related to volume overload." (PMID 32792012, 2020). "This study, in consonance with earlier research, shows that systemic inflammation marked by elevated IL-6, CRP, and TNF-α levels is associated with functional decline and malnutrition, two central components of the frailty syndrome." (PMID 33166358, 2020). "We also investigated the association between serum inflammatory markers (IL-6, IL-8, TNF-α, and CRP) and overall functional decline (ADL and TUG) and malnutrition." (PMID 33166358, 2020). "Conversely, THI patients with low levels of cytokines had lower risk of malnutrition during their stay in the ICU, IL-10 and TNFα (p < 0.001 to 0.01), IL-6 and IL-1β (p 0.23 to 0.900)." (PMID 31443251, 2019). "Recent studies have reported that NT-proBNP positively correlated with interleukin-6 and C-reactive protein and inversely correlated with serum albumin, so that NT-proBNP was considered a marker of inflammation or malnutrition." (PMID 29457529, 2018). "NT-proBNP has recently been reported to correlate with inflammatory markers (interleukin-6 and C-reactive protein), a malnutrition marker (serum albumin), and protein-energy-wasting syndrome." (PMID 29457529, 2018). "The adverse factors for malnutrition include disordered hormones, inflammatory cytokines (e.g., IL-6, TNFα, CRP), cigarette smoking, poor physical activity, and hypoxemia." (PMID 27669818, 2016). "The rats that were rescued from malnutrition in early life showed reduced transcription of NF-κB and IL-6 and increased transcription of IL-10 (an anti-inflammatory cytokine)." (PMID 25892856, 2015). "Low albumin levels were related to poor outcomes in patients with malignant diseases, reflecting both malnutrition and inflammation; it is worth noting that pro-inflammatory cytokines like interleukin 6 (IL-6) and tumour necrosis factor alpha (TNF-α) decrease albumin synthesis." (PMID 41228489, 2025). "These proteomic perturbations coalesce into a malnutrition-inflammation axis where sustained catabolic signaling, potentially via IL-6-mediated JAK/STAT activation, overrides nutritional anabolism, establishing MetS as both a biological filter and amplifier of therapeutic resistance." (PMID 41170367, 2025). "The modified NUTRIC Score (mNUTRIC score) does not include IL-6 and scores of 5-9 indicate a high malnutrition risk." (PMID 40735559, 2025). "According to the results, decreased levels of albumin (<3 g/dL) and hemoglobin (<11 g/dL), elevated homocysteine, CRP, IL-6 (>7.5 pg/mL), and IP-10 (>250 pg/mL) may attract medical processionals’ attention when diagnosing malnutrition." (PMID 40094974, 2025). "Previous studies have indicated that cancer can trigger the release of proinflammatory cytokines such as TNF-alpha, IL-6, and IL-1, leading to malnutrition through various processes such as CNS-driven anorexia, muscle wasting, changes in liver metabolism, and fat utilization and depletion." (PMID 40384994, 2025). "Independent effects of inflammatory states on malnutrition: inflammatory cytokines such as TNF-α and interleukin-6 are elevated in hemodialysis patients, and these factors exacerbate malnutrition by promoting proteolysis, inhibiting protein synthesis, and affecting energy metabolism." (PMID 39993135, 2025). "Previous reports have shown that individuals with obesity and malnutrition exhibit altered cytokine responses, including elevated IL-1β, IL-6, and TNF-α levels, which may worsen SARS-CoV-2 outcomes due to a heightened inflammatory state." (PMID 40565820, 2025). "In another analysis of ESRD patients, hs-CRP predicted malnutrition better than IL-6." (PMID 40004669, 2025).
malnutrition (continued). "Similarly, within the cytokine profiles, IL-6 and IL-10 levels were notably higher in the moderate/severe malnutrition group than in the other groups, as demonstrated by post hoc analysis." (PMID 38474705, 2024). "Elevated levels of IL-6 and CRP significantly increase the risk of muscle loss in terms of muscle mass and strength, leading to imbalances in muscle tissue synthesis metabolism, increased protein breakdown and malnutrition." (PMID 38760722, 2024). "Overall, low TC may be associated with poor prognoses in OSCC due to factors like increased lipid use by cancer cells, interleukin-6 overexpression, malnutrition, and weakened antitumor immunity." (PMID 39767804, 2024). "Furthermore, IL-6 can have a catabolic effect, promoting muscle wasting and inhibiting albumin synthesis, exacerbating malnutrition in MM patients." (PMID 37512137, 2023). "Based on the CONUT score, the prevalence of patients with moderate/severe malnutrition risk (score ≥ 5) was 10%, showing lower age, body mass index and fat mass, but higher IL-6 and IL-1β levels than subjects classified as not at risk (score 0–1)." (PMID 37111172, 2023). "The possible explanation could be in cancer related malnutrition, ROS and IL-6, induces hepcidin, which degrade ferroportin and halt the uptake of iron from small intestine and macrophage leading to unavailability of iron for heme synthesis." (PMID 36869395, 2023). "High levels of inflammatory cytokines, such as tumor necrosis factor α (TNF-α), interleukin (IL) 1β, IL-6, and CRP, together with loss of muscle mass, could account for malnutrition in affected patients." (PMID 37630691, 2023). "For example, in a recent cohort study of 534 community-dwelling older participants, malnutrition was diagnosed according to the GLIM criteria using an interleukin-6 cut-off value within the normal range of healthy persons (interleukin-6 > 3.84 pg/mL in men and >2.99 pg/mL in women)." (PMID 34282291, 2022). "We therefore hypothesize that the significant increase of IL-6 during chemoradiation is a multifactorial process including radiotherapy and concurrent cisplatin administration, mucositis, and malnutrition." (PMID 34773163, 2022). "Malnutrition promotes the phenotypic transformation of immune cells to pro-inflammatory phenotypes, secreting pro-inflammatory cytokines such as IL-1β, IL-6, IL-8, TNF-α, and IL-2, while anti-inflammatory cytokines such as IL-1 receptor antagonists, IL-4, IL-10, and IL-13 decrease." (PMID 35003070, 2021). "Interpretation of IL-6 production in malnutrition is made difficult by the findings of decreased, unchanged, and elevated levels when compared to the controls; however, when controlling for infection, IL-6 seems to be overall decreased." (PMID 31717370, 2019). "Furthermore, logistic regression analysis was performed after adjusting age, gender, malnutrition risk, AJCC stages, and change in IL-6 levels." (PMID 31010015, 2019). "Patients with higher NT-proBNP were older and showed lower dry weight and total body water and extracellular water, high prevalence of history of CVD events and malnutrition, decreased levels of creatinine, increased levels of IL-6 and hsCRP, and poorer cardiac function." (PMID 27870908, 2016). "Elevated levels of IL-6 and TNFα may primarily be related to infections, and support the observation that induction of an acute phase response is intact in malnutrition." (PMID 25153531, 2014). "However, malnutrition cannot be diagnosed based on IL-6 levels alone, as some patients with normal nutritional status according to the MNA or at no risk of nutritional-related complications according to the GNRI also had high IL-6 levels." (PMID 40094974, 2025).
malnutrition (continued). "Moreover, there is growing interest in the potential utility of integrating the CONUT score with markers of systemic inflammation, such as C-reactive protein (CRP) and interleukin-6, to more accurately capture the complex relationship between malnutrition, immune activation, and cardiac dysfunction." (PMID 40431475, 2025). "Third, due to financial constraints, we could only analyse three types of cytokines; exploring other cytokines, such as interleukin 6, interleukin 10and tumor necrosis factor α, could strengthen our understanding of the immune response to parasitic infections and malnutrition." (PMID 37111135, 2023). "It has been shown that an increase in RDW is triggered by nutritional deficiency caused by iron, vitamin B12, and folic acid deficiency and is associated with chronic inflammation and acute phase inflammation markers, such as C-reactive protein, tumor necrosis factor (TNF), and interleukin-6." (PMID 37404429, 2023). "Since IL-6 stimulates lipolysis, it is not clear whether increased levels of IL-6 are caused by malnutrition or inflammation, or both." (PMID 31749720, 2019). "The hyper-pyroptotic endotype was characterized by severe malnutrition (48.2% with MNA-SF ≤7) and elevated cytokines (median IL-6: 98.4 pg/mL)." (PMID 42058214, 2026). "Mechanistically, the bidirectional relationship between inflammation and malnutrition in IBD is mediated by proinflammatory cytokines (e.g., TNF, IL-6, IL-17), gut microbiota dysbiosis, and protein depletion." (PMID 41538674, 2026). "On the other hand, TB leads to malnutrition by triggering the release of pro-inflammatory cytokines such as TNF-α (tumor necrosis factor-alpha), IL-6, and IFN-γ, which increase basal metabolic rate, leading to excessive energy consumption." (PMID 40549763, 2025). "For example, elevated pro‐inflammatory biomarkers such as tumor necrosis factor‐alpha (TNF‐α), interleukin‐6 (IL‐6), and C‐reactive protein (CRP) are commonly seen in cases of malnutrition." (PMID 39817025, 2025). "Group B, which received the combined therapy, showed better results compared to group A, with reduced malnutrition grades and lower levels of inflammatory markers such as TNF-α, CRP, and IL-6 after treatment." (PMID 41281287, 2025). "Pro-inflammatory cytokines, including IL-6, IL-1β, and TNF-α, are released, activating pathways contributing to malnutrition development." (PMID 40507748, 2025). "It is particularly relevant to include inflammatory and functional biomarkers (such as CRP, IL-6, MIS, or PINI) as secondary endpoints to better characterise the malnutrition–inflammation complex and its response to therapy." (PMID 41228549, 2025). "In our study, patients with higher malnutrition scores had higher levels of inflammatory markers, such as CRP, IL-6 (Interleukin-6), and IL-10 (Interleukin-10), reinforcing the link between nutritional status and cytokine dysregulation." (PMID 40686821, 2025). "Future investigations should establish longitudinal monitoring frameworks integrating CRP, IL-6, and TNF-α to disrupt the “inflammation-malnutrition” vicious cycle and improve long-term outcomes." (PMID 40630494, 2025). "Malnutrition can induce a low-grade systemic inflammatory response with elevated serum levels of TNF, IL-1β, and IL-6." (PMID 38651412, 2024). "Previous studies have demonstrated a strong association between circulating inflammatory markers, such as CRP, IL-6, IL-10, and TNF-α, and malnutrition." (PMID 38474705, 2024). "The release of proinflammatory cytokines, such as IL-6, IL-1β, and TNF-α, is determinant of the pathophysiology of malnutrition." (PMID 39683535, 2024). "As for frailty definition, we adopted Fried’s frailty phenotype (FP), while malnutrition–inflammation syndrome was assessed using the Malnutrition–Inflammation Score (MIS) and circulating inflammatory cytokines (IL-6; TNFα; MCP-1)." (PMID 39203763, 2024).
malnutrition (continued). "Firstly, a higher level of inflammation indicated high levels of cytokines such as IL-1, and IL-6, tumor necrosis factor-alpha and CRP, which greatly accelerates the consumption of nutrition, leading to malnutrition and the progression of CRC." (PMID 37063910, 2023). "The parameter affected mortality are malnutrition, LOS ≥ 10 days, oxygen saturation <95%, leukopenia/leukocytosis, decreased ALC, prolonged PT/aPTT, AKI, ARDS, and increased of IL-6 level (p<0.05)." (PMID 37889917, 2023). "Interestingly, reduced PhA values and increased IL-6 levels were identified as independent predictors of moderate/severe risk of malnutrition, suggesting that the CONUT score might be a reliable tool for identifying patients at high risk of malnutrition." (PMID 37111172, 2023). "This study also verified that the MIS has a good correlation with the malnutrition indicators hemoglobin and prealbumin and inflammation indicators CRP, IL-6, TNF-a and ferritin in PD patients." (PMID 33413177, 2021). "Factors that negatively affect linear growth are increased levels of inflammatory cytokines such as interleukin-6 (IL-6) and tumor necrosis factor-α (TNF-α), malnutrition, suppression of serum IGF-1 levels, and disease severity." (PMID 33446154, 2021). "To examine the impact of malnutrition on other pro-inflammatory cytokines in T2DM, we measured the circulating levels of pro-inflammatory cytokines (G-CSF, GM-CSF, MCP-1, MIP-1β, IL-6, IL-7, IL-8, IL-12p70 and IL-1β) in LBMI and NBMI individuals." (PMID 33183277, 2020). "Considering that PTX3 is expressed in different tissues, including in the adipose tissue, this inflammatory biomarker seems to be more sensitive to inflammation-related malnutrition than CRP, IL-6, and TNF-α in this population." (PMID 31316299, 2019). "Individuals with RLD had higher prevalence of DM (46%), CVD (48%), and malnutrition (SGA>1; 31%), lower %HGS, higher concentrations of CRP and IL-6, and lower GFR." (PMID 29702682, 2018). "Malnutrition activates the nuclear factor kappa-B (NF-κB) pathway, promoting the release of proinflammatory cytokines such as tumor necrosis factor-alpha (TNF-α) and interleukin-6 (IL-6), which induce myocardial fibrosis and microvascular dysfunction." (PMID 41189988, 2025). "In addition, inflammatory factors such as IL-6 and TNF-α can promote muscle proteolysis, inhibit appetite, and then lead to malnutrition." (PMID 40630494, 2025). "In underweight individuals, non-diabetics exhibited higher IL-6 levels (median 24.1 pg/mL) than diabetics (median 16.8 pg/mL), possibly reflecting environmental stress or malnutrition-related inflammation." (PMID 41523554, 2025). "Pro-inflammatory cytokines including interleukin 6 (IL-6), interleukin 1β (IL-1β) and tumor necrosis factor α (TNF-α) are released, triggering several mechanisms which contribute to the pathogenesis of malnutrition." (PMID 36904164, 2023). "Moreover, malnutrition has been shown to exacerbate chronic inflammatory responses in diabetic patients through its influence on inflammatory mediator expression, including tumor necrosis factor-alpha (TNF-α) and interleukin-6 (IL-6)." (PMID 40977986, 2025). "Inflammatory cytokines such as TNF-α and IL-6 inhibit albumin synthesis, indicating that hypoalbuminemia in PD patients may be more attributable to systemic inflammation rather than malnutrition." (PMID 39281816, 2024). "Additionally, patients with malnutrition (according to the GLIM criteria) presented with decreased phase angle (PA) and standardized PA (SPA), decreased serum levels of albumin, transferrin and total cholesterol, accompanied by increased serum RCP and IL6." (PMID 35158762, 2022). "Therefore, in our underweight elderly patients, high levels of IL-6 and CRP might result from a cumulative action of immunoaging and undernutrition/malnutrition." (PMID 27274758, 2016).
malnutrition (continued). "Inflammatory cytokines, such as TNF, IL-6, and IFN-γ may downregulate lipolytic enzyme activity; however, the pathophysiological activities in IBD are more complex because of the chronic inflammation, malnutrition, and lipid malabsorption due to intestinal damage or resection." (PMID 35770006, 2022). "Finally, serum levels of some inflammatory mediators, such as interleukin-6 or interleukin-10, were not tested in our study, and how inflammatory cytokines in malnutrition patients with non-albicans candidemia played a role in the risk of mortality requires further investigation." (PMID 34579094, 2021). "In addition, frail older patients who were hospitalized had lower levels of albumin, which is a marker of malnutrition, and higher levels of CRP and IL-6 than non-frail individuals." (PMID 30249038, 2018). "However, it is important to emphasize that our study, similarly to all other large cohort studies, does not have data related to malnutrition and inflammation, such albumin, CRP, IL-6 or any other marker." (PMID 26091005, 2015).